BCKDK (branched chain keto acid dehydrogenase kinase)
Diseases named in the same sentence as BCKDK in open-access papers (continued):
Sharing a sentence is not in itself a finding about the gene and the disease.
breast carcinoma (7 papers, 2022 to 2025). "This study found that BCKDK was overexpressed in breast cancer, associated with poor prognosis, and implicated in tumor metastasis." (PMID 37460470, 2023). "In conclusion, identifying BCKDK as a biomarker for breast cancer metastasis facilitated further research on diagnostic biomarkers." (PMID 37460470, 2023). "First, BCKDK is negatively associated with a low recurrence-free survival rate, and genetic ablation or inhibition of BCKDK synergizes the cell cycle arrest effects of paclitaxel and increases cell death in breast cancer cells." (PMID 40507232, 2025). "This process ultimately enhances HRR in tumor cells, promoting tumor progression and resistance to DNA damage‐inducing therapy, positioning BCKDK as a potential therapeutic target in clinical breast cancer treatment." (PMID 40298908, 2025). "An increase in sensitivity to Adriamycin was also observed in BCKDK knockdown organoids derived from breast cancer patients." (PMID 40298908, 2025). "Collectively, these results demonstrate that the specific BCKDK inhibitor GSK180736A exhibits a strong synergistic effect with DNA damage‐inducing drugs in suppressing breast cancer." (PMID 40298908, 2025). "Kaplan–Meier analysis showed that breast cancer patients with low levels of BCKDK and p‐RNF8S157 survived significantly longer than those with higher levels of these markers." (PMID 40298908, 2025). "This indicates a strong association of BCKDK and p‐RNF8S157 levels with clinical staging and patient survival in breast cancer." (PMID 40298908, 2025). "A selective BCKDK inhibitor synergizes with clinical agents, suggesting a promising therapeutic strategy for breast cancer." (PMID 40298908, 2025). "This study reveals that BCKDK can localize within the nuclei of breast cancer cells, where it binds to and phosphorylates RNF8, thereby inhibiting the ubiquitin‐mediated degradation of RAD51." (PMID 40298908, 2025). "Meanwhile, treatment with Olaparib elevated the nuclear BCKDK in a dose‐dependent manner, suggesting BCKDK functions in the nuclear regulatory events in breast cancer." (PMID 40298908, 2025). "In vitro experiments demonstrated that inhibition of BCKDK expression reduced the migration of human breast cancer cells, while in vivo it decreased lung metastasis." (PMID 40438606, 2025). "Western blot analysis revealed that RAD51 ubiquitination levels were increased in BCKDK‐silenced breast cancer cells, an effect that was restored with RNF8 knockdown." (PMID 40298908, 2025). "Taken together, our results suggest that nuclear localization of BCKDK facilitates DNA damage repair by enhancing HRR in breast cancer." (PMID 40298908, 2025). "We next examined the role of the BCKDK/p‐RNF8/RAD51 axis in contributing to therapy resistance in breast cancer." (PMID 40298908, 2025). "This study has demonstrated that BCKDK localizes to breast cancer cell nuclei, where it binds to and phosphorylates RNF8, thereby blocking ubiquitin‐mediated degradation of RAD51 and enhancing HRR." (PMID 40298908, 2025). "Considering that paclitaxel is also used in the treatment of breast cancer, we also analysed BCKDK expression in three breast cancer cell lines." (PMID 36526674, 2023). "To determine the relationship between the BCKDK expression and the metastasis in breast cancer tissues, we obtained 10 tumor specimens, matched adjacent tissues, and axillary lymph node metastases, and assessed the BCKDK protein using IHC." (PMID 37460470, 2023). "We found that BCKDK can also upregulate the expression of EMT-related molecular markers in breast cancer." (PMID 37460470, 2023). "Together, these mouse models strongly indicated a metastasis-promoting role for BCKDK in breast cancer." (PMID 37460470, 2023). "The downregulation of BCKDK expression inhibited the migration of human breast cancer cells in vitro and diminished lung metastasis in vivo." (PMID 37460470, 2023).
breast carcinoma (continued). "In the breast cancer cells, knockdown of BCKDK with three separate siRNA also increased the sensitivity of MCF-7 and MDA-MB-468 breast cancer cells to paclitaxel." (PMID 36526674, 2023). "We measured the impact on paclitaxel sensitivity of inhibiting BCKDK in ovarian and breast cancer cell lines." (PMID 36526674, 2023). "In this study, we demonstrated that BCKDK was overexpressed in both clinical breast cancer specimens and breast cancer cell lines and that its expression was higher in triple-negative breast cancer with a high degree of malignancy and metastasis." (PMID 37460470, 2023). "To investigate BCKDK’s specific role in different malignant breast cancer cells, we examined the BCKDK protein expression of different breast cancer cell lines by western blot." (PMID 37460470, 2023). "In the breast cancer cells, BCKDK was abundant in MCF-7 cells, weakly detected in MDA-MB-468 cells and almost undetectable in MDA-MB-231 cells." (PMID 36526674, 2023). "However, this research demonstrated that BCKDK can also localize in the nuclei of breast cancer cells." (PMID 40298908, 2025). "Additionally, overexpression of BCKDK counteracted the anti‐tumor effects of Olaparib or Adriamycin in the breast cancer lines or organoids, respectively." (PMID 40298908, 2025). "Like breast cancer, increased BCKDK and reduced BCKDHA further retain the BCAAs in NSCLC cells." (PMID 40507232, 2025). "Notably, aberrant expression of the BCKDK/p‐RNF8/RAD51 axis correlates with breast cancer progression and poor patient survival." (PMID 40298908, 2025). "Additionally, we found that the expression of p‐RPA32 and formation of RAD51 foci, two markers of HRR, was reduced in BCKDK‐silenced breast cancer cells, while the expression of the Ku70 and formation of 53BP1 foci, two markers of NHEJ, remained unaffected." (PMID 40298908, 2025). "BCKDK perturbed the cadherin-catenin complex at the adherens junctions (AJs) and assembled focal adhesions (FAs) onto the extracellular matrix, thereby promoting the directed migration of breast cancer cells." (PMID 37460470, 2023). "Hence, this study revealed the mechanism of BCKDK regulating cell adhesion and breast cancer metastasis." (PMID 37460470, 2023). "To explore whether BCKDK could promote the malignant biological behaviors of breast cancer cells, we obtained MDA-MB-231 cells with a stable reduction in the BCKDK expression by using short hairpin RNA (shRNA) lentiviral constructs (shBCKDK(#1/#2))." (PMID 37460470, 2023). "The siRNA reduced the level of BCKDK in ovarian and breast cancer cells." (PMID 36526674, 2023). "However, the relevance of BCKDK to the development and progression of breast cancers and its function is unclear." (PMID 37460470, 2023). "Increased expression of BCKDK was correlated with poor outcome in breast cancer patients." (PMID 35785192, 2022). "Here, this work shows that nuclear‐localized branched‐chain α‐ketoacid dehydrogenase kinase (BCKDK) acts as a modulator of HRR, promoting cell resistance against DNA damage‐inducing therapy in breast cancer." (PMID 40298908, 2025). "Next, immunohistochemistry (IHC) was employed to examine BCKDK and p‐RNF8S157 expression in a retrospective cohort of 103 breast cancer patients with well‐characterized clinicopathological features." (PMID 40298908, 2025). "By examining DNA damage repair‐associated factors, we observed a large decrease in RAD51 protein levels following BCKDK knockdown, while RAD51 levels increased upon RNF8 knockdown in breast cancer cell lines." (PMID 40298908, 2025). "Regarding BCKA oxidation, direct evidence is still needed, such as measuring the BCKA oxidation metabolites to clarify how much BCKDK expression contributes to BCAA metabolism and, subsequently, breast cancer progression." (PMID 40507232, 2025).
breast carcinoma (continued). "We confirmed that inhibition of BCKDK with drugs or siRNA, or decreasing levels of BCAA in culture medium, increased the sensitivity of both ovarian and breast cancer cells to paclitaxel." (PMID 36526674, 2023). "Since the impact of BCKDK on TNBC metabolism and proliferation was examined in prior studies, we focused on studying the role of BCKDK in the adhesion and metastasis of breast cancer cells." (PMID 37460470, 2023). "However, the specific mechanism of BCKDK in the development of breast cancer remains unclear." (PMID 37460470, 2023). "Elucidating the mechanism by which BCKDK exerted its biological effect could provide a new theoretical basis for developing new markers for breast cancer metastasis and contribute to developing new therapies for the clinical treatment of breast cancer patients." (PMID 37460470, 2023). "To evaluate synergy between these inhibitors and paclitaxel, we used OVCAR-4, COV-362, COV-318 and FUOV-1 ovarian cancer cells which showed a range of expression levels of BCKDK and BCKDH as well as the three breast cancer cell lines." (PMID 36526674, 2023). "Taken together, these findings demonstrate that BCKDK‐mediated RNF8 phosphorylation at S157 plays a critical role in tumor progression and contributes to resistance against DNA damage‐inducing therapy in breast cancer." (PMID 40298908, 2025). "Moreover, forced expression of RNF8WT or RNF8S157D, but not RNF8S157A, promoted cell viability and colony formation in BCKDK‐overexpressing and endogenous RNF8‐silenced breast cancer cells." (PMID 40298908, 2025). "Collectively, these results indicate that BCKDK primarily regulates HRR rather than NHEJ in breast cancer cells." (PMID 40298908, 2025). "Here we show that inhibition of BCKDK using either siRNA or the chemical inhibitors 3,6-dichlorobenzothiophene-2-carboxylic acid (BT2/DCBC) or (S)-2-chloro-4-methylvaleric acid (CMVA) increases the sensitivity of ovarian and breast cancer cells to paclitaxel." (PMID 36526674, 2023). "Collectively, this study reveals a new role of BCKDK in regulating HRR, independent of its metabolic function, presenting it as a potential therapeutic target and predictive biomarker in breast cancer." (PMID 40298908, 2025). "To evaluate the potential clinical significance of the BCKDK‐mediated regulatory pathway in patient samples, we first assessed the levels of BCKDK, p‐RNF8S157, and RAD51 in 14 paired breast cancer lesions and adjacent noncancerous tissue samples." (PMID 40298908, 2025). "While it is not clear if BCKDK has been proposed to be involved in breast cancer cell metastasis via regulation of BCAT1 activity, it is of great interest to further investigate the relationship between BCKDK and BCAT1 in breast cancer development." (PMID 37460470, 2023).
Insulin resistance (7 papers, 2022 to 2025). Increased resistance towards insulin, that is, diminished effectiveness of insulin in reducing blood glucose levels. "It is likely that prolonged exposure to HFD-indued fat mass gain exacerbates insulin resistance, and thereby diminishes the inhibitory effect of hepatic BCKDK knockout on gluconeogenesis." (PMID 39389936, 2024). "Pyruvate dehydrogenase kinase 4 (PDK4) is a member of the PDK/BCKDK protein kinase family, which inhibits the pyruvate dehydrogenase complex by phosphorylation of its subunits, and it also has been previously shown to participate in apoptosis and insulin resistance." (PMID 35178098, 2022). "BCKDC is inactivated by another enzyme, branched-chain α-ketoacid dehydrogenase kinase (BCKDK), which is activated in insulin resistance." (PMID 41282284, 2025). "If elevated BCKA levels are indeed the main driver of insulin resistance, then lowering them can be accomplished through BCAT2 inhibition or BCKDK inhibition." (PMID 39007094, 2024). "The kinome analysis of T2D iHeps also predicted the kinases responsible for emergent signaling that may act as drivers of insulin resistance, including ROCK1/2, BCKDK, and MST4 for insulin-regulated phosphorylations." (PMID 40231468, 2025).
hepatocellular carcinoma (5 papers, 2020 to 2025). A malignant tumor that arises from hepatocytes. "Elevated expression of BCKDK has been observed in human hepatocellular carcinoma (HCC), resulting in the phosphorylation and subsequent inactivation of BCKDH complex." (PMID 40897695, 2025). "Another study also verified that BCKDK promoted hepatocellular cancer proliferation by MEK/ERK signaling pathway." (PMID 35498541, 2022). "BCKDK, which suppresses BCAA breakdown, has been identified as a pro-metastatic factor in colorectal cancer and hepatocellular carcinoma (HCC)." (PMID 41502503, 2025). "In addition, BCKDK promoted tumor growth and metastasis by interacting with SRC or mTOR in colon cancer or hepatic carcinoma." (PMID 35498541, 2022).
ovarian carcinoma (5 papers, 2022 to 2025). A malignant neoplasm originating from the surface ovarian epithelium. "In patients with ovarian cancer, a higher level of BCKDK is associated with advanced pathological grades." (PMID 37637065, 2023). "Although previous reports have associated elevated BCKDK expression with high-grade ovarian cancer and chemotherapy-resistant disease, the regulatory mechanisms of BCKDK expression and its role in metabolic reprogramming within TNBC remain unclear." (PMID 39025830, 2024). "Research findings suggest that the use of BCKDK inhibitors (BCKDKis) can rescue ovarian cancer resistance by reducing BCAA levels." (PMID 40687583, 2025). "Accordingly, BCKDK knockdown with shRNAs repressed ovarian cancer cell proliferation and migration in vivo and ex vivo." (PMID 37637065, 2023). "Inhibition of BCKDK using siRNA or two chemical inhibitors (BCKDKi) was synergistic with paclitaxel in both breast and ovarian cancer cells." (PMID 36526674, 2023). "In the ovarian cancer cells, immunoblotting demonstrated that BCKDK was highly expressed in COV-362, FUOV-1, IGROV-1 and OVCAR-8 and to lesser extent in COV-318 and OVCAR-3 cell lines." (PMID 36526674, 2023). "BCKDK DNA is amplified in 15.21% tumors of ovarian cancer patients, which is the second highest proportion just lower than that of uterine carcinosarcomas of 17.86%." (PMID 35498541, 2022). "However, while BCKDK is highly expressed in various ovarian cancer cell lines compared with normal ovarian epithelial cells, its expression is significantly lower in the COV-318 and OVCAR-3 cell lines." (PMID 40687583, 2025). "However, BCKDK is overexpressed in epithelial ovarian cancer (EOC), which promotes proliferation and migration via MEK–ERK." (PMID 40687583, 2025). "Moreover, BCKDK overexpression promotes ovarian cancer cell proliferation and migration by inducing the MEK/ERK pathway." (PMID 37637065, 2023). "However, in both breast and ovarian cancer cells, knockdown of BCKDK with each of the siRNA increased the caspase-3/7 activity induced by paclitaxel compared to cells transfected with a non-targetting siRNA." (PMID 36526674, 2023). "BCKDK expression is increased in high-grade ovarian cancer and in chemotherapy-resistant disease." (PMID 36526674, 2023). "Another investigation showed that inhibition of BCKDK by siRNA or chemical inhibitors could reduce BCAA levels and synergistically induce the antitumor effects of paclitaxel in breast and ovarian cancer cells." (PMID 37637065, 2023).
non-small cell lung carcinoma (4 papers, 2023). A group of at least three distinct histological types of lung cancer, including non-small cell squamous cell carcinoma, adenocarcinoma, and large cell carcinoma. "Transfection of anti-BCKDK siRNA into non-small cell lung cancer cells, including A549, HCC827, and H1299, reduced the expression of BCKDK, decreased BCKDE1α phosphorylation, and inhibited the proliferation of tumor cells in these cancers." (PMID 37637065, 2023). "In colorectal and non-small cell lung cancer, expression of BCKDK correlates with poor patient survival." (PMID 36526674, 2023). "In addition, BCKDK can alter the metabolism of non-small cell lung cancer." (PMID 38054015, 2023). "BCKDK as a relevant metabolic regulator through its actions on BCAA and citric acid, affects glycolysis and oxidative phosphorylation, thereby affecting the malignant progression of non-small-cell lung cancer." (PMID 37460470, 2023).
triple-negative breast carcinoma (4 papers, 2021 to 2024). An invasive breast carcinoma which is negative for expression of estrogen receptor (ER), progesterone receptor (PR), and human epidermal growth factor receptor 2 (HER2). "It has been reported that, like genetic and pharmacological inhibition of BCKDK, treating triple-negative breast cancer (TNBC) cells with doxorubicin downregulated BCKDK expression, reducing the intracellular concentrations of BCKAs." (PMID 37637065, 2023). "We found that the highly aggressive and metastatic triple-negative breast cancer cell lines MDA-MB-231, MDA-MB-468, and SUM159 possessed higher levels of the BCKDK protein, but these levels were considerably lower in the MCF-7 cell lines." (PMID 37460470, 2023).
developmental delay (3 papers, 2019 to 2022). "UCD and MSUD are intoxication-type IEM while BCKDK deficiency results in BCAAs deficits, and despite correct metabolic management, affected patients frequently suffer psychomotor delay, cognitive, behavioral and psychiatric conditions." (PMID 31235756, 2019). "In three siblings with severe developmental delays, microcephaly, autism spectrum disorder and epileptic encephalopathy, we identified a new homozygous in-frame deletion (c.999_1001delCAC; p.Thr334del) of BCKDK." (PMID 35216372, 2022).
myocardial infarction (3 papers, 2022 to 2024). Gross necrosis of the myocardium, as a result of interruption of the blood supply to the area, as in coronary thrombosis. "One approach to test this hypothesis may need to employ a global BCKDK depletion model, and to determine if the global BCKDK knockout could have any impact on cardiac function post pressure overload or myocardial infarction injury." (PMID 36991098, 2023). "In this study, the authors utilized BT2 (3,6-dichlorobenzo(b)thiopene-2-carboxylic acid), a BCKDK inhibitor, to promote BCKDH-mediated BCAA catabolism in myocardial infarction (MI)-operated mice, suggesting that restoring BCAA catabolism could ameliorate cardiomyopathy in humans." (PMID 38956299, 2024).
Parkinson disease (3 papers, 2019 to 2025). A progressive degenerative disorder of the central nervous system characterized by loss of dopamine producing neurons in the substantia nigra and the presence of Lewy bodies in the substantia nigra and locus coeruleus. "Summary of genetic, preclinical, and mechanistic evidence linking BCKDK to Parkinson’s disease." (PMID 40725241, 2025).
cardiac hypertrophy (2 papers, 2023 to 2025). "Finally, pharmacological inhibition of BCKDK in HFpEF mice significantly reversed the diastolic dysfunction and cardiac hypertrophy associated with HFpEF." (PMID 40521197, 2025). "Compared with the controls, BCKDK inactivation blunted diastolic dysfunction, cardiac hypertrophy and myocardial remodeling in response to chronic treatment with HFD/L-NAME." (PMID 40521197, 2025). "At tissue morphological level, inactivation of BCKDK did not change the degree of cardiac hypertrophy in response to pressure overload in either male or female cohort based on histology, heart weight or left ventricle weight /tibia length." (PMID 36991098, 2023). "Similar to the observation in the BCKDK-uKO mice, BT2 treatment significantly reduced cardiac hypertrophy without affecting body weight under HFpEF insult." (PMID 40521197, 2025).